CD40 (CD40 molecule)
Diseases named in the same sentence as CD40 in open-access papers (continued):
Sharing a sentence is not in itself a finding about the gene and the disease.
tumor (continued). "These cells express CD40, a crosslinking-dependent member of the TNFRSF, which plays a major role in modulating anti-tumor immune responses and is a popular target for immunotherapy." (PMID 39033322, 2024). "Compared to sham control mice, the CD45hi/CD11bhi compartment significantly expands in tumor-bearing mice and exhibits a myeloid-specific signature composed of VISTA, CD80, PD-L1, CTLA-4, MHCII, CD40, and CD68." (PMID 39123357, 2024). "This is reflected in the tumor-draining LN, as almost all migratory CD64+ cDC2 were CD40+ positive indicating that they were highly activated." (PMID 38631706, 2024). "Mature DCs express co-stimulatory molecules including CD80, CD86, CD40 and CD70, that enables DCs have the capacity to activate T cells and NK cells in tumor immune-surveillance, and directly kill tumor cells." (PMID 38554155, 2024). "CD40, a member of the tumor necrosis factor (TNF) receptor superfamily, plays an important role not only in the immune system but also in tumor progression." (PMID 39696986, 2024). "These scFv were utilized to coat a PLGA core, resulting in nanoengagers that display anti-CD40 scFv for engaging with macrophages and anti-CLDN18.2 scFv to interact with targeted tumor cells." (PMID 38468289, 2024). "For Vδ2 T cells, approaches include using humanized anti-BTN3A antibodies to enhance their tumor-targeting ability or employing engineered tumor-γδ TCR bispecific antibodies (e.g., CD40, CD1D) to boost their cytotoxic efficiency." (PMID 38774876, 2024). "Alongside this, administration of A. vulgaris extract significantly increased the percentages of CD40+ and MHCII+ as well as MHCII+CD86+ dendritic cells in the spleens of tumor-bearing mice." (PMID 38543072, 2024). "We assessed the expression of activation markers CD40 and CD86 in TdLNs and tumors from hsBCL9z96-treated CT26 tumor-bearing mice by flow cytometry." (PMID 38811552, 2024). "Lymphocyte related genes (CD3, CD8), B cell receptor related genes (CD40, CD79a), major histocompatibility complex (MHC) related genes (H2-Ab1, Ciita) were significantly downregulated in the tumor tissues of BDL mice." (PMID 38951890, 2024). "However, in situ, the priming of anti-cancer immunity by APCs may be hampered in HCC, since intra-tumoural activated DCs showed less expression of CD40 when compared to adjacent tissues in the majority of patients, especially in those with tumour suppressor gene mutations." (PMID 38440738, 2024). "The vaccine consists of Mannan‐BAM‐anchored irradiated whole tumor cells, Toll‐like receptor ligands [lipoteichoic acid (LTA), polyinosinic‐polycytidylic acid (Poly (I:C)), and resiquimod (R‐848)], and anti‐CD40 agonistic antibody (rWTC‐MBTA)." (PMID 38298111, 2024). "Both CD40 specific agonist antibody and recombinant soluble CD40 Ligand (CD40L) protein can effectively activate anti-tumor immune response in pre-clinical animal models." (PMID 39306655, 2024). "Since macrophage inducers (i.e., Nano/CD40) contain humanized CD40 scFv, we established CLDN18.2-overexpressing KPC subcutaneous tumor models in CD40-humanized transgenic mice." (PMID 38468289, 2024). "In contrast, the combination of C‐C motif chemokine ligand 2 (CCL2) and interferon gamma (IFN‐g) can drive an anti‐tumour phenotype in PDAC myeloid cells, and this is particularly important in the presence of CD40 agonist treatment." (PMID 38426634, 2024). "As well as this, CD40 activation triggers fatty acid oxidation (FAO) and glutamine metabolism, promoting epigenetic reprogramming of pro-inflammatory genes and an anti-tumor macrophage phenotype." (PMID 38533720, 2024). "Co-delivery of TAP siRNA and CpG ODNs to cDC1 inhibited tumor growth and exhibited superior antitumor activity than delivery of TAP siRNA alone in combination with CD40 Ab." (PMID 38231450, 2024).
tumor (continued). "Anti-CSF1R therapy hinders new TAM accumulation, including potential anti-tumor TAM subgroups, while anti-CD40 therapy alters existing TAMs, encompassing functionally distinct TAM subgroups as well." (PMID 38185636, 2024). "Remarkably, the CD64+ cDC2 displayed higher levels of the DC activation marker CD40 shown as median fluorescent intensity (MFI), compared with CD64− cDC2 and cDC1, when analyzed across all three different tumor stages." (PMID 38631706, 2024). "Previous studies using similar models of PDAC have demonstrated effective tumor control via the use of a combination of agonistic CD137 antibodies, PD-1 blockade, agonistic CD40 antibodies, and TLR stimulation." (PMID 39033322, 2024). "New therapeutic strategies are being addressed, employing anti-CD40 antibodies to increase their APC function and their secretion of IL-12, resulting in suppressed tumor growth in mice." (PMID 39682686, 2024). "CD40 agonism is an attractive way to enhance and/or replace T cell help and drive both CD8 T cell responses and T-cell mediated tumor immunity." (PMID 38903502, 2024). "BMMs were isolated from CD40-humanized transgenic mouse, and DiO-labeled KPC cells were co-cultured with DiD-labeled BMMs at a ratio of 1:10 (tumor cells:BMMs) for 6 h." (PMID 38468289, 2024). "Upon intratumoral implantation, CD40 mAb or PBS autonomously diffuses out of the reservoir and into the tumor through the nanofluidic membrane in a controlled and sustained manner." (PMID 36658712, 2023). "We found that β2AR signaling limits DCs function in the presence of tumor antigens by decreasing the expression of MHC-II, CD86, and CD40." (PMID 37006295, 2023). "For example, tumor-promoting TAMs can be reprogrammed into tumor-suppressor TAMs by PI3K-γ suppressors, CD40 agonists, anti-CD47 antibodies, and class-IIa HDAC suppressors." (PMID 37915049, 2023). "In one study, inducible MyD88/CD40 (iMC) CAR NK cells were extended to CAR NK cells and enhanced the tumor killing efficacy of CAR-NK by increasing cytotoxic function, cytokine secretion and proliferation." (PMID 37510993, 2023). "CD40 and CD40L interact to mediate anti-tumor immune responses by increasing immunogenic cell death (ICD) of tumor cells, activating antigen-presenting cells, producing proinflammatory factors and stimulating CD4+ and CD8+ T cells." (PMID 37666809, 2023). "We have previously demonstrated the therapeutic efficacy of an autologous whole tumor cell vaccine composed of irradiated entire tumor cells (rWTC) pulsed with mannan-BAM, TLR agonists, and anti-CD40 antibody (MBTA)." (PMID 37434263, 2023). "Moreover, the anti-tumoral activities of agonist molecules of CD40/4-1BB pathways have been evidenced in numerous preclinical models, but their clinical application has been hampered by tolerability issues mainly due to the engagement of the target outside the tumor (on-target off-tumor effects)." (PMID 38053848, 2023). "Expression levels of B7-H3, PD-L1, Tim-3, LAG3, VISTA, and STING as well as of CD40 and CD80 were significantly elevated in tumor boundary CD11c+ segments." (PMID 38044986, 2023). "We showed an increase in expression for a wide range of co-stimulatory molecules, CD40, CD80, OX40L, and STING on tumor boundary CD11c+ cells." (PMID 38044986, 2023). "We orthotopically implanted KPC2a tumor cells in REX3 mice and on day 7, administered αPD-L1, CD40 agonist or the combination." (PMID 36472588, 2023). "Few other proteins overlapped between our indices, and they can be grouped as immune stimulating (CD40 and CD40L43), angiogenic and tumor promoting (CXCL144 and PTN45), and immune suppressing (IL‐446 and IL‐547)." (PMID 36250429, 2023). "Further, combined treatment with CD40 agonists and gemcitabine/nab-paclitaxel improved TAM responses and anti-tumor T-cell clonal expansion, consequently facilitating PDAC control in mouse models." (PMID 37771596, 2023).
tumor (continued). "When CD40 binds to its ligand CD40L, this interaction mediates anti-tumoral immune responses by increasing ICD of tumor cells, upregulating the expression of MHC molecules and producing proinflammatory factors." (PMID 37243029, 2023). "There are multifactorial potential interactions between T-ALL and stroma that shape the myeloid anti-tumor immune response, including between CD47/SIRPα, PD-L1/PD-1, CD40/CD40L, and CD28/CD80/86." (PMID 36897988, 2023). "As shown in our previous study, our vaccine is composed of irradiated whole tumor cells (rWTC) labeled with mannan-BAM, Toll-like receptor (TLR) ligands, and an anti-CD40 antibody." (PMID 37434263, 2023). "On the other hand, in vitro activation of the immune checkpoint CD40/CD40L by endogenous expression of membrane-bound CD40L improves DC function and activates T-effector cells against several tumor types including CCA." (PMID 36980187, 2023). "The aggregation of CD20+ B cells and CD8+ T cells plays a crucial role in the tumour immune response through costimulatory signalling, such as CD40/CD40L, which triggers the tumour-killing effect of T cells." (PMID 36890557, 2023). "This vaccine is called rWTC-MBTA, comprising of irradiated autologous tumor cells (rWTC) mixed with mannan-BAM, TLR agonists, and anti-CD40 antibody (MBTA)." (PMID 37936697, 2023). "CD40, a member of the family of tumor necrosis factor (TNF) receptors, is displayed by tumor cells and antigen-presenting cells (APCs), including macrophages." (PMID 37426676, 2023). "Many tumors express CD40 and engagement with T cells expressing CD40L can trigger tumor cell apoptosis." (PMID 37810959, 2023). "TAM-1s expressed high protein levels of major histocompatibility complex (MHC) class II, CD40, and CD86, suggesting a role in promoting anti-tumor adaptive immune responses." (PMID 37209684, 2023). "Comparing the mRNA level of CD40 in PDAC and controls confirmed a significantly higher level in tumor tissue." (PMID 37838778, 2023). "Most agonist mAbs targeting CD40 are of the IgG1 subclass with different levels of affinity to CD40 and depend on crosslinking with FcγRs in order to facilitate CD40 aggregation for APCs activation as well as an ADCC activity against tumor cells." (PMID 37215135, 2023). "In the same cases, the mean tumor staining intensity was 25 for VEGFR-2 (mean TBR 0.7), 7 for EGFR (mean TBR 0.9), 7 for IGF-1R (mean TBR 0.5), and 18 for CD40 (mean TBR 2)." (PMID 36979961, 2023). "The combination of immune stimulators of CD40 and TLR highly inhibited the tumor growth in mice, whereas the combination of TLR7 with an activator of TLR9 reduces NF‐κB activation and compromises vaccine efficacy." (PMID 36464889, 2023). "CD40 is a superfamily member of TNF receptor and expresse on many antigen-presenting cells (APCs) as well as some tumor cells." (PMID 36816959, 2023). "In IMGT/mAb-DB, we find one blocking mAb anti-CD40, lucatumumab (mAbID 176), that mediates ADCC and ADCP against tumor cells." (PMID 37215135, 2023). "CD8 T cell depletion abrogated tumor control and decreased mice survival, indicating that CD8 T cells are required for the response to RT+CTLA4i+anti-CD40." (PMID 37620372, 2023). "The gene expression profile in CMS3 TME of KRASmut shows upregulation of CD40, CTLA4, ARG1, STAT3, IDO, and CD274, making it a key regulator of immune suppression in TME regions surrounding the KRASmut tumor." (PMID 36831441, 2023). "CD40, a member of TNF receptors, is expressed on the surface of cells such as DCs, monocytes, B cells, and some tumor cells." (PMID 37046842, 2023). "CD40-activated B cells can directly expand antigen-specific CD8+ T cells, and mice vaccinated with tumor antigen-pulsed CD40-B cells showed a significant reduction in tumor growth and size." (PMID 38269112, 2023).
tumor (continued). "In addition, platelets release increased levels of soluble CD40, which is a known inhibitor of regulatory T cell recruitment that may promote the immunosuppressive microenvironment and eventually form an environment conducive to tumor growth." (PMID 35250826, 2022). "When CD40LG antibodies are used to disrupt the CD40/CD4OLG system’s function, it leads to the suppression of tumor cells." (PMID 35879761, 2022). "In the tumor, this effect was most prominent in the Flt3L+NDV cohort, with significantly higher expression of activation markers (e.g. MHC I/II, CD80, CD40), particularly in cDC1s, suggesting greater-than-additive effect when combining NDV and Flt3L." (PMID 36418317, 2022). "Besides targeting CD40, intratumoral injection of fms-related tyrosine kinase 3 ligand or granulocyte–macrophage colony-stimulating factor might also be promising options, because they recruit and activate DCs at the tumor site." (PMID 35136110, 2022). "Flow cytometry showed that CD40 expression was significantly upregulated on M1 TAM and this correlated with a significant increase in expression of iNOS protein in the tumor of KC-HPC-API compared with KC-HPC mice." (PMID 35892872, 2022). "In a murine melanoma model, tumor antigen vaccination based on anti-CD40 and poly-IC increased the number of CD8+ T cells in tumor tissue and delayed tumor growth." (PMID 35413927, 2022). "Cluster #4 presented with the most abundant expression of maturation markers including LAMP3, CD80, CD40, the migration marker CCR7, and overexpressed the tumor Secretory cDC2 signature, thus #4 was labeled mmDC." (PMID 35418195, 2022). "Upon activation through Toll-like receptors (TLRs), DCs upregulate MHC and co-stimulatory molecules, including CD40 and CD80/CD86, all of which interact with T cells to promote a proinflammatory or anti-tumor response." (PMID 36248881, 2022). "CD40 is a member of the TNF receptor superfamily and licenses dendritic cells to promote anti-tumor T-cell activation and re-educate macrophages to destroy tumor stroma upon activation." (PMID 35795050, 2022). "Here, CD24+CD38+ Bregs promote tumour progression through a mechanism involving CD40 and CD40L interactions with cancer cells that subsequently leads to the secretion of IL-10 and TGFβ that sustain tumour proliferation." (PMID 35350071, 2022). "GEGFR, CD40, SPATA2, ZBP1, ID1, and MYC showed a significant CNV amplification in most tumour types; however, TLR3, PDHB, FAS, and MAP3K showed a significant CNV deletion in most tumour types." (PMID 36186436, 2022). "Treatment of PDFS cells with RGFP966 and 5’-AZA also significantly increased the mRNA expression of other tumor suppressors, including EGR1, PTEN, STAT1, and immune stimulatory receptor CD40." (PMID 35646715, 2022). "Further, miR-125b inhibits M2 polarization through the repression of IRF4 and, when overexpressed in macrophages, increases in vitro CD8+ T-cell priming, tumor clearance, and CD80/86, CD40, MHCII, and IFN-γ receptor (IFN-γR) expression." (PMID 36248881, 2022). "The CD79A/CD40 co-stimulatory structural domain confers enhanced proliferative capacity of CAR-T cells and increased anti-tumor effects in mouse models." (PMID 35741714, 2022). "Lesson from pre-clinical and clinical studies of next-generation CD40 antibodies, together with mechanistic knowledge of the cellular pathways that mediate efficacy and toxicity, may enable the development of additional cell- and tumor-selective agonists with an improved therapeutic window." (PMID 35911742, 2022). "Recurrent TNFRSF14 mutations in DHLs lead to reduced expression of HVEM, a TNFR family protein and tumor suppressor which inhibits BCR signaling, abnormal stroma activation, and CD40 signaling through BTLA stimulation." (PMID 35303910, 2022). "CD40 agonistic mAbs can induce TAMs to secrete high levels of matrix metalloproteinase 13 (MMP13), an enzyme that supports tumor control by degrading fibrotic tissue." (PMID 36679900, 2022).
tumor (continued). "For example, therapies targeting OX40, CD40, and CD27 have achieved favorable progress in various tumor treatments, including for patients with lung cancer." (PMID 35879761, 2022). "On the other hand, JQ-1 is capable of facilitating crosstalk between antigen-presenting dendritic cells and T cells through the CD40/CD40L costimulatory pathway, leading to activation of tumor-specific CTLs." (PMID 35292660, 2022). "In this context, it has been previously shown that the combination of anti-CD40 and anti-CTLA-4 antibodies accompanying a liposomal peptide or adenoviral vaccine considerably enhanced the CTL responses against tumor cells." (PMID 36091050, 2022). "Some of the most highly expressed genes across tumor types are CCL19, CD40, BIRC3, LAMP3, LY75 (see review for details)." (PMID 36230990, 2022). "We also observed significant increases in the numbers of CD40+ and CD40L+ cells in the K7M2 tumor microenvironment, which confirmed the results of the RNA-seq analysis." (PMID 35292660, 2022). "TAM programming with agonistic anti-CD40 increased both Ly6Chigh TAMs and the intra-tumoral accumulation of TCR-engineered T cells, which finally increased tumor cell apoptosis." (PMID 35585567, 2022). "Conversely, FAT-WT patients had suppressive TME with high expression of CCL2, CXCL12, CXCL14, CD40, ENTPD1, TGFB1, and VEGF; these factors have been confirmed to promote angiogenesis, invasion, and metastasis of tumor cells." (PMID 35836939, 2022). "In our study, we found that NETs act on HUVECs to trigger the release of various tumor-related factors, such as ANGPT2, ECM, CD40, and IL-8." (PMID 36172371, 2022). "Further, PTT with aFn14-PBNP resulted in a unique tumor cellular immunophenotype consisting of thermal dose-dependent enhanced expression of CD137L, CD80, CD86, and CD40." (PMID 35957076, 2022). "Inhibitors of PI3Kγ or mTOR as well as agonists of CD40, TLR4, -7, -8, or -9 can repolarize macrophages towards a proinflammatory phenotype promoting tumor suppression in preclinical studies." (PMID 36237314, 2022). "The results showed that CD276, CD40, CD274, CD44, and NRP1 expression was exclusively upregulated in cluster 0 (invasive tumor)." (PMID 36685583, 2022). "The main pathway for CD40L/CD40 signaling in the TME is likely through myeloid cells; we and others have shown that tumor-infiltrating macrophages and DCs express CD40 receptor, but there is very little to no expression of CD40 receptor on CD8+ T cells." (PMID 36073543, 2022). "Firefly luciferase-tagged colon-26 cells were injected subcutaneously into the spleen so that tumor cells would be engrafted in the liver, followed by a combination of K3-SPG-ISV/anti-CD40-ISV." (PMID 35136110, 2022). "We then assessed the expression of CD40 (a T cell costimulation marker) on M1 TAM (gated as MHC-II+ and CD206−) within the tumor from KC-HPC vs. KC-HPC-API mice." (PMID 35892872, 2022). "First, CD40 stimulation, via viral delivery of CD40L, can support the ability of viruses to promote tumor immunity in murine models and cancer patients." (PMID 34282297, 2022). "In pre-clinical studies, GammabodyTM molecules targeting CD40, CD1d and EGFR efficiently engage Vγ9Vδ2 T-cells to kill tumor cells expressing these antigens." (PMID 35784326, 2022). "Owing to the expression of CD40 on a wide range of immune cells, including CD4+ T-cells, macrophages, and B-cells, activation of this pathway mediates anti-tumor immune responses." (PMID 35027068, 2022). "We also assessed the efficacy of PV/anti-CD40 against spontaneous tumors arising in the MMTV-PyMT model and found that this combination inhibited tumor progression and doubled the overall survival." (PMID 35788566, 2022). "Lysate from MTP-treated tumors showed an even stronger upregulation of chemokines involved in immune cell recruitment, including CXCL9, CCL5, CXCL10, CD40 and CXCL16, compared to both control and MTX-treated tumor lysates." (PMID 36397148, 2022).